LMO1 (LIM domain only 1)
Description:
May be involved in gene regulation within neural lineage cells potentially by direct DNA binding or by binding to other transcription factors.
Synonyms: RBTN1; RHOM1; TTG1
Tractability: No criterion of Open Targets' tractability assessment is met for any kind of drug.
Gene: Protein-coding gene on chromosome 11 (8,224,309 to 8,268,752, reverse strand). Ensembl gene ENSG00000166407.
Subcellular location: Nucleus
Pathways (Reactome):
Gene expression (Transcription): RUNX1 regulates transcription of genes involved in differentiation of HSCs
Gene Ontology:
Molecular function: protein binding; transcription coactivator activity
Biological process: positive regulation of transcription by RNA polymerase II
Cellular component: nucleoplasm; nucleus
Genetic constraint (gnomAD): Loss-of-function variants: 9 observed, 16.61 expected, observed/expected ratio (o/e) 0.54, 90% interval 0.33 to 0.95. The upper end of that interval is the gene's LOEUF score, 0.95, which puts it in group 4 of 6, group 1 being the genes least tolerant of losing a copy. Missense variants: 176 observed, 201.88 expected, observed/expected ratio (o/e) 0.87, 90% interval 0.77 to 0.99. Synonymous variants: 76 observed, 76.18 expected, observed/expected ratio (o/e) 1, 90% interval 0.83 to 1.21.
Homologues: Orthologues: chimpanzee LMO1 (100% identical), dog LMO1 (100% identical), macaque LMO1 (100% identical), rat Lmo1 (99% identical), mouse Lmo1 (99% identical), zebrafish lmo1 (97% identical), rabbit LMO1 (95% identical), guinea pig LMO1 (94% identical), tropical clawed frog lmo1 (94% identical), pig LMO1 (92% identical). Paralogues in human: LMO3 (83% identical), LMO4 (41% identical), LHX9 (40% identical), LMO2 (40% identical), LHX2 (39% identical), LHX4 (38% identical), LHX6 (37% identical), LHX3 (36% identical), LHX8 (35% identical), LMX1A (35% identical), LMX1B (35% identical), ZFHX4 (33% identical), and 8 more.
Diseases named in the same sentence as LMO1 in open-access papers:
LMO1 is named in the same sentence as 42 diseases in open-access papers, as found by Europe PMC text mining. Sharing a sentence is not in itself a finding about the gene and the disease. The quoted sentences say what the papers report.
neuroblastoma (54 papers, 2013 to 2026). Neuroblastoma (NB) is the most common solid, extracranial childhood tumor. "LMO1, a transcriptional cofactor implicated as an oncogene in neuroblastoma, provides one such example." (PMID 41495882, 2026). "Thereafter, the relationship between LMO1 polymorphisms and neuroblastoma risk was further determined in other epidemiological case‒control studies among subject populations of various ethnicities." (PMID 38937681, 2024). "This discovery was opposite to a meta-analysis publication that assessed the association between LMO1 gene polymorphism and neuroblastoma risk." (PMID 38937681, 2024). "In our current study, we used genetic editing in the zebrafish to define the in vivo mechanism underlying the striking association between the germline rs2168101 G → T noncoding polymorphism in the first intron of lmo1 and the risk of developing neuroblastoma." (PMID 37183825, 2023). "In an earlier publication, we showed that one of the most significant neuroblastoma predisposition loci in our study was the rs2168101 G → T transversion that resides within the first intron of the LMO1 gene." (PMID 37183825, 2023). "The SNP rs2168101 within the SE of the neuroblastoma oncogene LMO1 influences neuroblastoma susceptibility through differential GATA TF binding and regulation of LMO1 expression." (PMID 37548349, 2023). "A super-enhancer in the first intron of LMO1 affects neuroblastoma susceptibility by regulating LOM1 expression." (PMID 33712565, 2021). "Germline single nucleotide polymorphism (SNP) risk alleles are associated with increased LMO1 expression in neuroblastoma cell lines and primary tumors." (PMID 31819055, 2019). "In childhood neuroblastoma, our previous genome-wide association study (GWAS) has shown that polymorphisms at the LMO1 gene locus are strongly associated with susceptibility to tumor formation." (PMID 31819055, 2019). "In order to investigate the association between these LMO1 polymorphisms and neuroblastoma in eastern Chinese children, we performed a multi-center study with 313 cases and 716 controls recruited from three regions of East China." (PMID 30406033, 2018). "In fact, LMO1 was recently identified through a genome-wide association study as an oncogene associated with neuroblastoma, a neuroendocrine tumor that occurs in childhood." (PMID 30038707, 2018). "Clinical analysis indicated that the risk alleles of LMO1 (rs110419 A, rs4758051 G, rs10840002 A, rs204938 C) were in significant association with metastatic and high-risk neuroblastoma." (PMID 30406033, 2018). "The variant A allele eradicates GATA3 binding site and associates with a decrease in the LMO1 expression levels in neuroblastoma primary tumor." (PMID 30406033, 2018). "The association between LMO1 SNPs with neuroblastoma susceptibility was replicated in several independent cohorts from US, UK, and Italy." (PMID 30406033, 2018). "We confirmed that four variants (rs110419, rs4758051, rs10840002, and rs2168101) in the LMO1 gene were associated with a decreased risk of neuroblastoma in our study population." (PMID 30406033, 2018). "In vitro study further showed that loss- or gain-of-function of LMO1 suppressed and promoted proliferation of neuroblastoma cell lines, respectively." (PMID 30406033, 2018). "The variant allele, rs110419, found in 55% of neuroblastoma patients compared to 45% in healthy controls, results in a gain of function mutation that increases LMO1 expression." (PMID 30200332, 2018). "The association of LMO1 with neuroblastoma suggests the possible involvement of LMO1 in other types of neuroendocrine cancers, such as neuroendocrine lung cancer." (PMID 30038707, 2018). "The LMO family of genes had been previously implicated in the development of leukemia and breast cancer, but this was the first time LMO1 had been linked to neuroblastoma." (PMID 30200332, 2018).
neuroblastoma (continued). "In conclusion, we found that four LMO1 SNPs were associated with a decreased neuroblastoma risk in eastern China populations." (PMID 30406033, 2018). "Since LMO1 was established as a neuroblastoma risk gene, the association between LMO1 SNPs and neuroblastoma susceptibility has been replicated in several different ethnic groups." (PMID 30406033, 2018). "The rs2168101 G>T located in the LMO1 super-enhancer was also reported to modify neuroblastoma susceptibility by the same research group." (PMID 30406033, 2018). "A polymorphism within a super-enhancer in the first intron of LMO1 that preserves an evolutionarily conserved GATA factor binding motif predisposes to neuroblastoma." (PMID 29445148, 2018). "Previous genome-wide association studies (GWASs) have discovered a number of neuroblastoma susceptibility genes in Caucasians including LIM domain only 1 (LMO1)." (PMID 30406033, 2018). "To further elucidate the association between LMO1 polymorphisms and neuroblastoma risk, we combined our present results the data from our earlier study." (PMID 29029458, 2017). "Although this is a relatively large sample for investigating the correlation between LMO1 polymorphisms and neuroblastoma risk in the Chinese, several limitations still exist." (PMID 29029458, 2017). "In summary, we have further confirmed the protective effect of LMO1 polymorphisms on neuroblastoma susceptibility in a Chinese population." (PMID 29029458, 2017). "Consistent with our earlier findings, we observed that LMO1 polymorphisms were associated with a decreased risk of neuroblastoma." (PMID 29029458, 2017). "This combined analysis improves the statistical power for assessing the impact of LMO1 polymorphisms on neuroblastoma risk." (PMID 29029458, 2017). "In the present case-control study, we further verified the effect of LMO1 polymorphisms on neuroblastoma risk in a Northern Chinese population." (PMID 29029458, 2017). "Thereafter, case-control studies conducted with Italian, African-American and Northern Chinese populations verified LMO1 polymorphisms to be factors affecting neuroblastoma risk." (PMID 29029458, 2017). "This approach confirmed the recently identified causal variant (rs2168101) at the LMO1 locus shown to disrupt a canonical GATA binding site in neuroblastoma, and identified several other variants that warrant further study." (PMID 28545128, 2017). "The larger sample in the combined analysis highlights the important protective effect of LMO1 polymorphisms on neuroblastoma risk." (PMID 29029458, 2017). "In 2016, we conducted the first epidemiological study on the effect of LMO1 polymorphisms on neuroblastoma susceptibility in a Southern Chinese population." (PMID 29029458, 2017). "Here, we assessed the relationship between LMO1 polymorphisms and neuroblastoma risk in an additional 118 cases and 281 controls." (PMID 29029458, 2017). "We previously investigated the association between LMO1 polymorphisms and neuroblastoma risk in a Southern Chinese population." (PMID 29029458, 2017). "Previous genome-wide association and validation studies suggest that LIM domain only 1 (LMO1) gene polymorphisms affect neuroblastoma susceptibility." (PMID 29029458, 2017). "In this work, we used Taqman methodology to genotype four LMO1 polymorphisms (rs110419 A > G, rs4758051 G > A, rs10840002 A > G and rs204938 A > G) in 118 neuroblastoma cases and 281 controls from Northern China." (PMID 29029458, 2017). "A previous genome-wide association study revealed that LMO1 polymorphisms were associated with predisposition to neuroblastoma." (PMID 29029458, 2017). "We further explored the association between LMO1 gene rs110419 A > G polymorphism and combined effects of protective genotypes with neuroblastoma susceptibility in stratification analysis by age, gender, sites of origin, and clinical stages." (PMID 27009839, 2016).
neuroblastoma (continued). "The most common polymorphic alleles have been identified at the LIM-domain-only gene LMO1 locus which is significantly associated with advanced stage neuroblastoma." (PMID 28035989, 2016). "Previous genome-wide association study (GWAS) indicated that several common genetic variations (rs110419 A > G, rs4758051 G > A, rs10840002 A > G and rs204938 A > G) in the LIM domain only 1 (LMO1) gene were associated with neuroblastoma susceptibility." (PMID 27009839, 2016). "This has been done for a handful of disorders such as the FTO (fat mass and obesity-associated) locus in obesity, LMO1 (LIM domain only 1) in neuroblastoma predisposition and BCL11A (B-cell lymphoma/leukaemia 11A) in sickle cell anaemia [116•]." (PMID 27628759, 2016). "The association between LMO1 gene polymorphisms and neuroblastoma susceptibility was confirmed by their following expanded GWAS study with a total of 2817 neuroblastoma cases and 7473 controls." (PMID 27009839, 2016). "The aim of this study was to evaluate the correlation between the four GWAS-identified LMO1 gene polymorphisms and neuroblastoma risk in a Southern Chinese population." (PMID 27009839, 2016). "More potentially functional SNPs located in the LMO1 gene should be investigated, such as the rs2168101 G > T polymorphism that was found to be associated with neuroblastoma recently." (PMID 27009839, 2016). "In the current case-control study with 256 neuroblastoma cases and 531 healthy controls, we verified that the LMO1 rs110419 A > G polymorphism was associated with a decreased neuroblastoma risk." (PMID 27009839, 2016). "With these in mind, in this hospital-based case-control study, we aimed to determine the relationship between LMO1 gene polymorphisms and neuroblastoma susceptibility in a Southern Chinese population with 256 cases and 531 controls." (PMID 27009839, 2016). "Apart from neuroblastoma, the LMO1 gene polymorphisms were also associated with acute lymphoblastic leukemia susceptibility." (PMID 27009839, 2016). "They found that four single nucleotide polymorphisms (SNPs) in the LMO1 gene (rs110419 A > G, rs4758051 G > A, rs10840002 A > G and rs204938 A > G) were associated with neuroblastoma susceptibility." (PMID 27009839, 2016). "Aberrant LMO1 locus resulting from a duplication event was associated with more advanced disease and unfavorable survival in neuroblastoma patients." (PMID 27009839, 2016). "In summary, the present hospital-based case-control study confirmed that the LMO1 gene rs110419 G allele was associated with decreased neuroblastoma susceptibility in a Southern Chinese population." (PMID 27009839, 2016). "They further found that the LMO1 gene polymorphisms were associated with neuroblastoma susceptibility, and the most significant SNP is rs110419 A > G polymorphism with a combined P = 5.2*10−16." (PMID 27009839, 2016). "Since then, the association between the four LMO1 SNPs and neuroblastoma have been validated in African-Americans, Italians, and a Northern Chinese population." (PMID 27009839, 2016). "Very recently, we have found a polymorphism in the first intron of LMO1 that can influence neuroblastoma susceptibility by affecting differential GATA transcription factor binding." (PMID 28035989, 2016). "In addition to neuroblastoma, genetic variants in the LMO1 gene also contribute to susceptibility to acute lymphoblastic leukemia (ALL)." (PMID 38937681, 2024). "LMO1, LMO2, and LMO3 are functionally redundant T-ALL oncogenes, so, we reasoned that loss of lmo1 expression in zebrafish might stimulate the upregulation of other lmo family members during neuroblastoma pathogenesis." (PMID 37183825, 2023). "Thus, conversion of the regulatory GATA to a TATA allele in the first intron of LMO1 reduced the neuroblastoma-initiation rate by preventing formation of the adrenergic cell state." (PMID 37183825, 2023). "Polymorphisms in LMO1 are associated with increased susceptibility to develop neuroblastoma." (PMID 31819055, 2019).
neuroblastoma (continued). "In addition, LMO1 occupancy was associated with enrichment of transcription factors that have previously been shown as members of the ADRN neuroblastoma CRC, including PHOX2B, HAND2, TBX2, and ISL15,19–21 (left)." (PMID 31819055, 2019). "We next further explored whether the haplotypes of the five LMO1 SNPs would modify neuroblastoma risk." (PMID 30406033, 2018). "LMO1 at 11p15.4 was identified as a neuroblastoma susceptibility locus in a previous GWAS." (PMID 30406033, 2018). "Association between LMO1 haplotypes and neuroblastoma susceptibility." (PMID 30406033, 2018). "Finally, functional analysis should be performed to investigate underlying biological mechanisms of LMO1 SNPs' protective effects on neuroblastoma." (PMID 30406033, 2018). "Moreover, the association between the LMO1 super-enhancer polymorphism rs2168101 and a decreased neuroblastoma risk was validated in the southern and northern Chinese population alone as well as in the combined case series." (PMID 30406033, 2018). "LMO1 gene polymorphisms and neuroblastoma susceptibility in eastern Chinese population." (PMID 30406033, 2018). "First, LMO1 rs110419 was shown to significantly decrease the risk of neuroblastoma (heterogeneous: adjusted OR = 0.62, 95% CI = 0.46–0.82; homogenous: adjusted OR = 0.65, 95% CI = 0.44–0.97; additive: adjusted OR = 0.76, 95% CI = 0.63–0.92; dominant: adjusted OR = 0.63, 95% CI = 0.48–0.82)." (PMID 30406033, 2018). "In addition, LMO1 gene single nucleotide polymorphisms (SNPs) reportedly affect susceptibility to acute lymphoblastic leukemia and neuroblastoma." (PMID 29029458, 2017). "Therefore, to further confirm the relationship between LMO1 polymorphisms and neuroblastoma risk, we performed the current hospital-based case-control study using subjects from Northern China." (PMID 29029458, 2017). "Therefore, multicenter studies with larger sample size are needed to confirm the roles of LMO1 in neuroblastoma susceptibility." (PMID 27009839, 2016). "In the expanded GWAS with 2251 neuroblastoma cases and 6097 controls restricted to European ancestry, four polymorphisms (rs110419 A>G, rs4758051G>A, rs10840002 A>G and rs204938 A>G) in the LMO1 locus on 11p15.4 were found to confer neuroblastoma susceptibility." (PMID 27021521, 2016). "However, future studies with larger sample size and functional experiments should be conducted to further explore the role of LMO1 and underlying mechanisms in neuroblastoma carcinogenesis." (PMID 27009839, 2016). "Lmo1 has been implicated as an oncogene in human neuroblastoma and may contribute to tumorigenesis in this mouse model." (PMID 23765217, 2013). "A heritable polymorphism within regulatory sequences of the LMO1 gene is associated with its elevated expression and increased susceptibility to develop neuroblastoma, but the oncogenic pathways downstream of the LMO1 transcriptional co-regulatory protein are unknown." (PMID 31819055, 2019). "In neuroblastoma, single nucleotide variants in the SE within the first intron of LIM domain only 1 (LMO1) eliminate the binding motif of GATA and cause LMO1 dysfunction." (PMID 40032852, 2025). "Among 127 neuroblastoma primary tumours, 80% carried the G/G phenotype (G/G = 102, G/T = 25, T = 0), and LMO1 mRNA expression was significantly decreased in G/T tumours compared to G/G tumours." (PMID 38542080, 2024). "An example is the LMO1 SNP rs2168101 G > T in neuroblastoma, which induces addiction to LMO1 expression." (PMID 38844984, 2024). "SNP rs2168101 G>T has been shown to be specifically associated with neuroblastoma and to be located at the GATA3 binding site within the LMO1-SE region." (PMID 38542080, 2024). "Because the TATA/TATA genotype causes low LMO1 expression and LMO1 is required for the adrenergic CRC to form, we predict that the TATA/TATA genotype would protect against neuroblastoma in patients with germline activating mutations of PHOX2B." (PMID 37183825, 2023).